CCNB2 (cyclin B2)
Diseases named in the same sentence as CCNB2 in open-access papers (continued):
Sharing a sentence is not in itself a finding about the gene and the disease.
viral myocarditis (1 paper, 2021). Myocarditis that is caused by an infection with a viral agent. "By contrast, the genes in CCNB2 low-expression group were associated with complement and coagulation cascades, viral myocarditis, and antigen processing and presentation." (PMID 34838000, 2021).
tumor (104 papers, 2009 to 2026). "We then further mined lncRNAs and miRNAs that interact with CCNB2 and constructed a risk model using only three survival-related lncRNAs to reconstitute patients and explore the tumor microenvironment to improve precise treatment." (PMID 38300330, 2024). "CCNB2 was the only gene with consistentchanges in the tumor and the associated PBMCs as wellas the other cancer types." (PMID 34455715, 2021). "CCNB2 is highly expressed in a variety of human tumor tissues and peripheral blood, and it is associated with the clinical stage and metastasis of the tumor." (PMID 30995921, 2019). "CCNB2 which encodes the cyclin B2 protein is additionally involved in checkpoint control and its overexpression was positively associated with the tumour size and lymph and node metastasis in NSCLC." (PMID 31877723, 2019). "Furthermore, cell cycle genes such as CDK5, CCNA2, CCNB1, and CCNB2, associated with tumor relapse and metastasis, are more highly expressed in DAB2IP-low Luminal A tumors." (PMID 39418101, 2024). "Moreover, even though the tumor-supporting effects of CCNB2 have been verified in NPC, the underlying mechanism remains largely unclear." (PMID 38166895, 2024). "By contrast, luminal cluster 2 was enriched in a proliferative gene signature (Mki67, Ccnb2, Cdk1, Ccnb1 and Ccnd1), which may be associated with cycling progenitors fuelling tumour growth." (PMID 38238426, 2024). "In GSE19750, only CCNB2 (F = 6.271, p = 0.013) was significantly associated with tumor grade." (PMID 35693556, 2022). "RMS patients with tumour diameters > 5 cm were more susceptible to high CCNB2." (PMID 34838000, 2021). "Our results further revealed that CCNB2 expression is associated with tumour size." (PMID 34838000, 2021). "CCNB2, encoding the member of the cyclin family, could promote tumor progression by facilitating cell proliferation and maintain normal G2/M transition." (PMID 32411535, 2020). "Importantly, high CCNB2 expression was strongly associated with tumor stage (P = 0.01), and high ASPM expression was associated with new tumor events (P = 0.03)." (PMID 32685486, 2020). "The underlying mechanisms of CCNB2 on tumor progression need to be further clarified." (PMID 30254986, 2018). "Moreover, the protein and mRNA levels of Pbk, Mcm2, Cyclin B2, Cyclin D2 and Cyclin A were markedly increased in menin-deficient tumours and dramatically rescued to normal levels by β-catenin ablation in mice." (PMID 25517963, 2014). "This subclass was characterised by under-expression of cell-cycle or proliferation-associated genes such as CCNA2 and CCNB2. these features could explain the less aggressive behaviour of these tumours." (PMID 19826428, 2009). "In addition, CDK1, CDC20, CCNA2, CCNB1 and CCNB2 expressions may be involved in the regulation of monocytes and tumor-associated macrophages (TAMs) in HCC, respectively." (PMID 36605491, 2023). "Abnormal CCNB2 expression may cause malfunctions of the G2/M checkpoint, leading to gene mutation, structural changes in the chromosome and abnormal growth of cell number, thus leading to the development of tumours." (PMID 35349480, 2022). "IL-6 and B-cell lymphoma 2 showed downregulated expression in tumor tissues, while cyclin-dependent kinase 1, cyclin-dependent kinase 2, cyclin B1, Erb-B2 receptor tyrosine kinase 2, and cyclin B2 were upregulated." (PMID 41650055, 2026). "Further analysis of the MMH cohort revealed that a high or low expression (transcript levels lower or higher than the cohort median) of KPNA2/FOXM1/CCNB1/CCNB2 is associated with ER, PR, HER2, and Ki67 status, molecular subtype, tumor grade, and AJCC stage." (PMID 40002266, 2025). "The expression of four genes (TOP2A, CDK1, CCNA2, and CCNB2) with high scores in module 1 were more in tumor samples and have been identified by GEPIA analysis." (PMID 38895552, 2024). "Overexpression of CCNB1, CCNB2, DLGAP5, and ASPM is associated with tumor progression and poor prognosis." (PMID 39045407, 2024).
tumor (continued). "After clarifying the relationship between CCNB2 and inhibitory immune checkpoints, we proceeded to analyze the effect of CCNB2 on tumor-immune infiltration." (PMID 38300330, 2024). "Further analysis highlighted four specific hub genes—CCNA2, CCNB2, CDK1, and TOP2A—that showed significantly higher expression in HBV‐associated HCC tumor samples compared to normal samples in the GEPIA database." (PMID 38895552, 2024). "It was found that CCNB2 knockdown appreciably constrained the tumorigenic activity of the cells, while JMJD6 and PFTα reversed the effect of CCNB2 to increase the tumor size in the mice." (PMID 38166895, 2024). "The CDK1, CDK5, CDC20, CCNA2, CCNB1 and CCNB2 expression levels (tumor sample: n = 369 vs. normal sample: n = 160) were upregulated in HCC group compared with the non-carcinoma group (Analysis by GEPIA dataset)." (PMID 36605491, 2023). "The result also showed that CDK1, CDK5, CDC20, CCNA2, CCNB1 and CCNB2 mRNA expression levels within tumor tissues were significantly increased compared with the adjacent normal tissues." (PMID 36605491, 2023). "As previous studies found, CCNB2 was a cell cycle–related gene that can promote the proliferation and tumor growth of GC cells." (PMID 35938042, 2022). "Based on previous research and results of tumour formation experiments in nude mice, the present study focused on CCNB2 as the primary research objective." (PMID 35349480, 2022). "Tumour weight decreased after CCNB2 was knockdown, which suggested that tumour proliferation ability decreased following CCNB2 knockdown." (PMID 35349480, 2022). "We used tumour tissues from nude mice for the WB assay and found that CCNB2 was correlated with JAG1 expression." (PMID 35349480, 2022). "A total of 1085 tumor tissues and 291 normal tissues were used to assess the expression of CCNB2 in these tissues." (PMID 34354775, 2021). "Specific cyclin genes such as Ccna2, Ccnb1, Ccnb2, and Ccne1 encoding CYCLIN A2, B1, B2, and E1, respectively, were also upregulated in MMTV-R26Met tumours." (PMID 34646365, 2021). "Consistent with the in vitro data, we further noticed that CCNB2 promoted tumor growth of TNBC cells in vivo." (PMID 34354775, 2021). "Gene set enrichment analysis (GSEA) revealed that the genes in MAD2L1 and CCNB2 groups with high expression were mainly related to the mechanism of tumour metastasis and recurrence." (PMID 34838000, 2021). "We further found the correlations between TNBC patients' prognosis, clinical pathological features, and CCNB2 expression in tumor tissues." (PMID 34354775, 2021). "We found that CCNB2 promoted tumor growth in vivo, and we further should assess the effects of CCNB2 on the migration, invasion, and apoptosis of TNBC cells." (PMID 34354775, 2021). "We further detected the effects of CCNB2 on the proliferation of TNBC cells in vitro and in vivo and assessed the effects of CCNB2 in on tumor growth of TNBC cells." (PMID 34354775, 2021). "In OS, a majority of differentially expressed genes were described as being involved in cell cycle regulation, including Cdk1 and cyclin B2, which were found upregulated in this tumor." (PMID 34358066, 2021). "We further performed immunoblot assays to confirm the alteration of CCNB2 expression in tumor tissues from mice." (PMID 34354775, 2021). "According to the results of Chi-square test, there was an obvious difference in CCNB2 expression between patients with different tumour sizes (p < 0.001)." (PMID 34838000, 2021). "We found that the protein of TTK, CCNB1, and CCNB2 much stronger expressed in tumor cells and immune cells in NSCLC when compared with that in normal lung tissues." (PMID 32969465, 2020). "In summary, we confirmed TTK, CCNB1 and CCNB2 were pro-oncogenes that mainly expressed in tumor cells and immune cells." (PMID 32969465, 2020). "In tumor tissues, CCNB2, DYNC1LI1, SPC25 and KIF18A expressions were mainly detected in the cytoplasm, and KIF11 expression was detected mainly in the cytoplasm and nucleus." (PMID 33111935, 2020).
tumor (continued). "CCNB2 expression was associated with tumor stage (P = 0.01), and ASPM expression was associated with new tumor events (P = 0.03)." (PMID 32685486, 2020). "CTLA4, MZB1, NIP7, and BUB1B in ADC, as well as GNG11 and CCNB2 in SCC, are novel top hub genes in modules associated with tumour size, SUVmax, and recurrence-free survival." (PMID 31877723, 2019). "ROC curve indicated that CCNB2, FBXO5, KIF4A, MCM10, and TPX2 exhibited excellent diagnostic efficiency for normal and tumor tissues." (PMID 30254986, 2018). "In Chinese non-small-cell lung cancer (NSCLC) patients, high expression levels of CCNB2 protein were positively correlated with the tumor size, status of differentiated degree, distant metastasis, lymph node metastasis, as well as clinical stage." (PMID 29977454, 2018). "Due to loss of biopsy cores, insufficient tumor cells present in the cores or affluence of necrotic tissue, 72/80 FFPE specimens were evaluated for CCNB2, KIAA0101, SLC27A2, ASPM, and CDCA7 immunostaining." (PMID 23282137, 2013). "The study found that PC3 cells with decreased CCNB2 expression substantially suppressed tumor growth, accompanied by a notable decrease in ki67, a marker indicative of tumor proliferation, thus preliminarily suggesting that the knockdown of CCNB2 inhibits cellular proliferative activity." (PMID 41049007, 2025). "JMJD6 OE or PFTα treatment mitigated the anti-tumor effects of si CCNB2 both in vitro and in vivo." (PMID 38166895, 2024). "To date, there have been a number of studies on the role of CCNB2 in tumor progression." (PMID 38300330, 2024). "In particular, CCNA2, CCNB2, CDK1, and TOP2A were found to be significantly upregulated in HBV‐positive HCC tumor samples and may serve as promising diagnostic biomarkers." (PMID 38895552, 2024). "Other studies which investigated proliferation-related markers in BC, including CCNB2 and Ki67, demonstrated that high expression of these biomarkers was associated with the features of aggressive tumour behaviour, such as LVI, large tumour size, and shorter survival." (PMID 36418517, 2023). "In addition, more research results show that the overexpression level of CCNB2 protein is significantly related to the degrees of tumor differentiation, tumor size, lymphatic metastasis, distant metastasis, and clinical stage." (PMID 36714024, 2023). "To summarize, we found that ASPM, CCNB2, and CDK1 expressions were significantly associated with tumor purity, which could be a sign that ASPM, CCNB2, and CDK1 played specific roles in immune infiltration in ACC." (PMID 35693556, 2022). "The tumour growth was inhibited following CCNB2 knockdown, which indicates that CCNB2 may activate HCC progression." (PMID 35349480, 2022). "In GSE76021, only CCNB2 (F = 7.569, p = 0.001) was significantly related to tumor stage." (PMID 35693556, 2022). "We found that knockdown of the CCNB2 gene inhibited tumorigenesis, while inhibition of CCNB2 knockdown increased tumour volume and weight; this finding suggested that CCNB2 may promote the occurrence and development of HCC." (PMID 35349480, 2022). "Although further studies are needed to verify our hypothesis, our results indicated that CCNB2 participates in the tumor immune microenvironment mainly by regulating B cells." (PMID 34908101, 2022). "Moreover, there was a positive relationship between CCNB2 expression and tumor purity (cor = 0.268, p = 0.021) and infiltrating level of dendritic cells (cor = 0.238, p = 0.043)." (PMID 35693556, 2022). "The detection of circulating CCNB2 mRNA in serum may be clinically relevant for monitoring tumour metastasis and for screening treatment methods." (PMID 35349480, 2022).
tumor (continued). "They then found that the autophagy inhibitor 3-MA restored the pro-tumor effects of circ-CCNB2 overexpression on irradiation-resistant PCa cells, demonstrating the role of circ-CCNB2 in regulating the radiosensitivity of PCa, and which was attributed to autophagy." (PMID 36358938, 2022). "The overexpression of CCNB2 was positively correlated with tumor number, tumor size, tumor thrombus, and metastasis of HCC, which may contribute to the poor prognosis of HCC patients." (PMID 33868991, 2021). "In addition, we need to expand the number of tumor samples and conduct long-term follow-up on the survival of patients in order to further clarify the relationship between CCNB2 and TNBC." (PMID 34354775, 2021). "We found that CCNB2 expression was decreased in CCNB2-depleted tumor tissues." (PMID 34354775, 2021). "Moreover, we constructed the animal models to investigate the effect of CCNB2/SASP/PGE2 axis on tumor growth in vivo." (PMID 34512164, 2021). "The total of 114 patients was divided into CCNB2 low- and high-expression groups according to the expression levels of CCNB2 in tumor tissues; we noticed that 46 patients showed CCNB2 low expression (40.3%), and the remaining 68 patients (59.7%) showed high CCNB2 expression." (PMID 34354775, 2021). "We noticed CCNB2 expression was obviously enhanced in tumor tissues." (PMID 34354775, 2021). "Interestingly, nostatistically significant difference was reported for CCNB2 protein level in terms ofpatient age, tumor grade, tumor size, ER/ PR/HER2 status, stage and axillary lymph nodestatus." (PMID 34455715, 2021). "Importantly, we noticed that CCNB2 expression was obviously correlated with tumor size (p = 0.022∗) and pTNM stage (p = 0.021∗) of patients with TNBC." (PMID 34354775, 2021). "To further confirm our previous in vitro results, we detected whether CCNB2 promoted tumor growth of TNBC cells through an in vivo model." (PMID 34354775, 2021). "In addition, in vitro experiments showed that high levels of CCNB2 can suppress the expression of E-cadherin to inhibit the invasion and metastasis of tumor cells." (PMID 33381151, 2020). "The curves indicated that the high CCNB2 expression was associated with shorter survival times compared with the low CCNB2 expression in HCC patients with tumor stage 2 (log-rank P = 0.022) and tumor stage 3 (log-rank P = 0.011)." (PMID 31886163, 2019). "Additionally, the effect of CCNB2 on overall survival of patients with different tumor stages were also assessed." (PMID 31886163, 2019). "However, no significantly different survival times were observed between patients with high CCNB2 expression levels and patients with low CCNB2 expression levels at tumor stage 1 (log-rank P = 0.073)." (PMID 31886163, 2019). "Importantly, we found that vemurafenib therapy substantially down-regulated nuclear protein levels of cyclin B2, from about 30% of tumor cells in the vehicle-treated tumors to about 2% in vemurafenib-treated tumors." (PMID 26636651, 2015). "In addition, the expression of CCNB2 may help regulate B cells, and plays an important role in tumor microenvironment." (PMID 34908101, 2022). "However, the migration potential was significantly inhibited by CA074, the inhibitor for Cathepsin B (Lenti-CCNB2+CA074 vs. Lenti-CCNB2: 47.9±5.57 vs. 69.5±3.91%, P=0.005), which suggested that Cathepsin B secreted from CCNB2-related senescent cells promoted tumor migration." (PMID 34512164, 2021). "Collectively, we thought CCNB2 could contribute to tumor growth of TNBC cells in mice." (PMID 34354775, 2021). "Moreover, the expression of CCNB2 was related to tumour size." (PMID 34838000, 2021). "The expression of Ccna2, Ccnb2, and Cdk1 were low, which could reduce G1/S-phase arrest and the transition from G2 to M phase, furthermore enhanced the ability of anti-apoptosis of tumor stem cells." (PMID 28163656, 2017).
tumor (continued). "A heatmap of the 11 mRNA expression levels of the tumor samples displayed that the seven genes, including CCNB1, CCNB2, CHEK1, FEN1, PTTG1, RACGAP1, and UBE2C, had higher expression levels in the tumor tissue." (PMID 41009526, 2025). "The significant overlap highlights the dual roles of genes such as TOP2A, CCNB2, BUB1, TPX2, and EZH2 in both tumor initiation and tumor progression, reinforcing their potential as key biomarkers for PCa." (PMID 40626556, 2025). "Our examinations showed a significant overexpression of five genes (CCNB1, CCNB2, PTTG1, RACGAP1, and UBE2C) in the tumor samples." (PMID 41009526, 2025). "MET was enriched in proliferating tumor cells featuring high levels of markers of cell cycle progression such as cyclins b1 and b2 (CCNB1, CCNB2), proliferating-cell nuclear antigen (PCNA) and Ki67 (MKI67) and likely define yet another subset of MBM." (PMID 38386085, 2024). "These genes formed a highly interconnected network, with key central nodes such as AURKB, CEP55, CCNB2, and MCM10, suggesting their involvement in common pathways potentially driving aggressive tumor behavior and contributing to poor patient prognosis." (PMID 39596419, 2024). "HMGB2 in POSTN+ fibroblasts is predicted to bind to PLD2, LRP5, MYLK, and CD44 on tumor cells, regulating downstream genes, including BIRC5, CCNA2, CCNB1, CCNB2, CDC20, and MKI67, which are related to the cell cycle." (PMID 38519500, 2024). "Two genes (CCNB2, CDC20) were found to be related to necrosis, inflammation, hyperplasia, and tumor." (PMID 36820589, 2023). "To further study the function of CCNB2 in HCC, we conducted a tumour formation experiment in nude mice." (PMID 35349480, 2022). "In this study, three key genes, CDC20, CCNB2, and BUB1, have been identified in youth-onset NSCLC tumor tissues based on the TCGA and GEO cohorts." (PMID 35859798, 2022). "After analyzing 15 samples, we discovered that the expression intensity of CCNB2 in the LUAD and LUSC tissues was significantly higher than that in the non-tumor lung tissues (p < 0.05)." (PMID 35928585, 2022). "Immunohistochemistry (IHC) was conducted to detect the CCNB2 expression in 12 LUAD and LUSC tissues as well as three non-tumor lung tissues." (PMID 35928585, 2022). "In conclusion, we constructed a five DEGs (CCNB2, CDK1, DTL, GMNN, and UBE2C)-based prognostic signature for ACC and first identified GMNN as a novel tumor biomarker for predicting the malignant progression, mitotane efficacy, and prognosis of ACC." (PMID 36539849, 2022). "Next, we confirmed the positive linear correlations between the mRNA expression of MKI67 vs. CCNA2, CCNB1, CCNB2, and CCNE2, suggesting their role in tumor progression." (PMID 36151566, 2022). "Herein, we found that CCNB2 was highly expressed in human TNBC tissues and correlated with the prognosis and clinical pathological features including tumor size (p = 0.022∗) and pTNM stage (p = 0.021∗) of patients with TNBC." (PMID 34354775, 2021). "Further, ISL1 enhanced tumor growth and targeted the downstream genes CCNB1, CCNB2, and C-myc in GC." (PMID 33962568, 2021). "And our results showed that the expression levels of MAD2L1 and CCNB2 correlated with the overall survival of patients with RMS and the clinical stage of the tumor." (PMID 34838000, 2021). "In this study, a systemic analysis was performed to reveal CDK1, CCNB2, and CDC25A as the hub genes; the expression of these genes increased in tumor tissues and predicted poor prognosis in LUAD." (PMID 34446056, 2021). "Our study authenticated the regulation role of CCNB2 on SASP cytokines secretion and tumor malignant transformation." (PMID 34512164, 2021). "Consistent with the expression results analyzed by ONCOMINE, the expression levels of CDK1, CCNB1, CCNB2, MAD2L1, and TOP2A assessed by TCGA data were all upregulated in tumor tissues compared with the normal controls (all P < 0.05)." (PMID 31886163, 2019).